KRT76 (keratin 76)
Description:
Probably contributes to terminal cornification.
Synonyms: KRT2B; KRT2P; HUMCYT2A
Tractability: PROTAC: ubiquitination databases record sites on it.
Gene: Protein-coding gene on chromosome 12 (52,768,155 to 52,777,345, reverse strand). Ensembl gene ENSG00000185069.
Pathways (Reactome):
Developmental Biology: Formation of the cornified envelope; Keratinization
Gene Ontology:
Molecular function: protein binding; structural constituent of skin epidermis
Biological process: cytoskeleton organization; intermediate filament organization; keratinization
Cellular component: extracellular exosome; nucleus; cytosol; intermediate filament; keratin filament
Genetic constraint (gnomAD): Loss-of-function variants: 41 observed, 42.12 expected, observed/expected ratio (o/e) 0.97, 90% interval 0.76 to 1.26. The upper end of that interval is the gene's LOEUF score, 1.26, which puts it in group 5 of 6, group 1 being the genes least tolerant of losing a copy. Missense variants: 755 observed, 734.5 expected, observed/expected ratio (o/e) 1.03, 90% interval 0.97 to 1.09. Synonymous variants: 306 observed, 279.75 expected, observed/expected ratio (o/e) 1.09, 90% interval 1 to 1.2.
Homologues: Orthologues: chimpanzee KRT76 (98% identical), macaque KRT76 (94% identical), dog KRT76 (86% identical), mouse Krt76 (75% identical), rat Krt76 (73% identical), rabbit KRT76 (69% identical). Paralogues in human: KRT3 (76% identical), KRT5 (60% identical), KRT2 (59% identical), KRT6A (58% identical), KRT1 (58% identical), KRT6B (58% identical), KRT6C (58% identical), KRT75 (56% identical), KRT4 (55% identical), KRT79 (52% identical), KRT77 (52% identical), KRT73 (51% identical), and 56 more.
Diseases named in the same sentence as KRT76 in open-access papers:
KRT76 is named in the same sentence as 43 diseases in open-access papers, as found by Europe PMC text mining. Sharing a sentence is not in itself a finding about the gene and the disease. The quoted sentences say what the papers report.
oral cancer (5 papers, 2013 to 2024). "We observed KRT76 downregulation in patients with gingivobuccal cancers – a sub site of oral cancer, which is etiologically associated with peculiar tobacco and betel quid chewing habit common in India." (PMID 23936238, 2013). "KRT76 depletion has also been linked with human oral carcinomas and premaligant epidermal changes." (PMID 25340345, 2014). "Hence, we selected in-vivo model systems: the hamster model to demonstrate K76 downregulation during sequential progression of oral cancer, and the KO mice model to evaluate the effect of KRT76 loss." (PMID 23936238, 2013). "Immunohistochemistry and KRT76 knockout mouse experiments showed that the expression of KRT76 was downregulated in normal oral tissues, oral precancerous tissues, and oral cancer tissues." (PMID 35096060, 2022). "Gene expression profiles of oral cancer obtained by other groups have also shown consistent downregulation of KRT76." (PMID 23936238, 2013). "The KRT76-KO mice data underlines the potential of KRT76 being an early event although this loss is not sufficient to drive the development of oral cancers." (PMID 23936238, 2013). "We have previously reported that Krt76−/− mice, which have reduced expression of tight junctions in the epidermis but not in the tongue, show increased susceptibility to oral cancer and systemic inflammation that correlates with an increase in Tregs in the oral cavity." (PMID 39625985, 2024). "Our current findings suggest that the loss of KRT76 may not be a sole molecular event leading to oral cancer development." (PMID 23936238, 2013).
oral squamous cell carcinoma (5 papers, 2013 to 2023). "KRT76 is the most significantly downregulated gene encoding a structural protein in human oral squamous cell carcinoma (OSCC) and is strongly associated with poor prognosis." (PMID 37076985, 2023). "Krt76 is the most significantly downregulated gene encoding a structural protein in human oral squamous cell carcinoma (OSCC) and correlates strongly with poor prognosis." (PMID 30143634, 2018). "The keratin 76 downregulation enhanced the accumulation of T regulatory cells, leading to a drop in the anti-tumor response in oral squamous cell carcinoma." (PMID 37046726, 2023). "KRT76 was downregulated expressed in human oral squamous cell carcinomas and correlated with a poor prognosis." (PMID 35675043, 2022). "Keratin 76 (Krt76) is an epithelial differentiation marker that is downregulated in oral squamous cell carcinomas, correlating with poor prognosis." (PMID 30143634, 2018). "Krt76 downregulation in human oral squamous cell carcinomas (OSCC) correlates with poor prognosis." (PMID 30143634, 2018).
periodontitis (3 papers, 2022 to 2024). An acute or chronic inflammatory process that affects the tissues that surround and support the teeth. "Other possibly relevant downregulated genes to the pathogenesis of T2DM-related periodontitis are keratin 76, critical for epidermal integrity, and the PLA2G2F, as PLA2s are involved in host defense and barrier function." (PMID 38241313, 2024).
gastric cancer (2 papers, 2018 to 2019). A primary or metastatic malignant neoplasm involving the stomach. "Using Krt76-deficient mice (Krt76−/−), we have demonstrated an interesting and novel role for Krt76 in keeping the immune system in check and preventing oral and gastric cancer." (PMID 31225508, 2019). "When mice are given a chemical carcinogen in the drinking water, tongue and gastric cancer formation is accelerated in Krt76−/− mutant mice." (PMID 31225508, 2019).
Autoimmunity (1 paper, 2023). The occurrence of an immune reaction against the organism's own cells or tissues. "Keratin 76, in particular, is required for barrier-forming tight junctions in skin squamous epithelial cells and, in what might portend a role in CNS autoimmunity, has been shown to possess immunomodulatory properties." (PMID 37858244, 2023).
cholesteatoma (1 paper, 2014). A pathologic process characterized by the proliferation of keratinizing squamous epithelium resulting in the accumulation of keratin and cells in the middle ear and/or mastoid. "Other keratins had increased levels of expression in non-cholesteatoma tissues: KRT76, 79 (Tympanic membrane), KRT15 (EACS), and KRT7, 8, 18, 19 (Mucosa)." (PMID 25093596, 2014).
cyst (1 paper, 2018). A sac-like closed membranous structure that may be empty or contain fluid or amorphous material. "However, between the ages of 4 and 8 months all Krt76−/− mice spontaneously developed a large cyst (up to 17 mm in diameter) between the lower jaw and the forelimbs." (PMID 30143634, 2018).
Griscelli syndrome (1 paper, 2014). Griscelli syndrome (GS) is characterized by silvery gray sheen of the hair and hypopigmentation of the skin which can be associated to neurological impairment (type 1), immunodeficiency (type 2) or be isolated (type 3). "In-depth analysis of three mutants, Krt76, Myo5a (a model of human Griscelli syndrome) and Mysm1, provides validation of the screen." (PMID 24721909, 2014).
keratoconus (1 paper, 2023). A degenerative, structural disorder of the eye, characterized by a cone-shaped protrusion of the cornea. "Among all the listed keratins only KRT1, KRT4, KRT76, and KRT78 are upregulated in keratoconus all the other keratins are not differentially expressed." (PMID 37279397, 2023).
Lymphadenopathy (1 paper, 2018). Enlargement (swelling) of a lymph node. "We conclude that loss of Krt76 results in splenomegaly and lymphadenopathy, indicative of systemic inflammation." (PMID 30143634, 2018). "We have found that Krt76-null mice exhibit a marked inflammatory disease phenotype with systemic components: splenomegaly and lymphadenopathy." (PMID 30143634, 2018).
oral cavity tumours (1 paper, 2018). "We next compared the incidence of oral cavity tumours in Krt76+/+, Krt76+/− and Krt76−/− mice." (PMID 30143634, 2018).
squamous cell carcinoma (1 paper, 2022). A carcinoma arising from squamous epithelial cells. "The cytoplasmic/membranous expression of KRT76 in oral epithelial cells was high in normal epithelial tissues, and its expression was reduced in squamous cell carcinoma." (PMID 35096060, 2022).
stomach tumour (1 paper, 2018). "However, Krt76−/− mice started developing tumours in the squamous stomach by week 16 and by week 28 89% of the mice had a stomach tumour." (PMID 30143634, 2018).
cancer (15 papers, 2010 to 2025). A tumor composed of atypical neoplastic, often pleomorphic cells that invade other tissues. "In the 8-mRNA signature (KCNJ18, RPE65, GRIA1, LCN15, C11orf21, ANXA13, FSIP2 and KRT76), the expressions of some mRNAs have been reported to have significant associations with the survival in some cancers." (PMID 35675043, 2022). "Instead the cancer susceptibility of Krt76−/− mice correlated with a higher number of Tregs in secondary lymphoid organs and an enhanced accumulation of Tregs in the tongue and squamous stomach, which increased further in the tumour microenvironment." (PMID 30143634, 2018). "We envision a number of possible ways in which KRT76 loss contributes to cancer development." (PMID 23936238, 2013). "The Krt76−/− mouse serves as a model to explore the link between chronic inflammation and cancer, providing an opportunity to examine the impact of aberrant epithelial differentiation and consequent chronic inflammation on tumorigenesis." (PMID 30143634, 2018). "The expression of KRT76 was the highest in normal head and neck oral mucosal epithelial tissues, it was almost not expressed in other tissues of the body, and its expression was reduced when cancer occurs." (PMID 35096060, 2022). "Among the 224 differently regulated proteins that are more abundant in male D sites are tricarboxylate transport protein (SLC25A1), proteasome β-4 subunit (PSMB4), and type II cytoskeletal 2 oral keratin (KRT76), all with known roles in cancer (expression profiles)." (PMID 35566209, 2022). "Here we evaluate the role of KRT76 downregulation in oral precancer and cancer development." (PMID 23936238, 2013).
tumor (13 papers, 2011 to 2024). "We propose that upon loss of Krt76 the increase in the immunosuppressive Treg infiltrate leads to a failure in anti-tumour immunity linked to exaggerated suppression of anti-tumour-associated antigen-reactive lymphocytes." (PMID 30143634, 2018). "Many of the tumours had areas that were LacZ-negative, indicating downregulation of Krt76 or loss of Krt76-expressing cells." (PMID 30143634, 2018). "We now present data indicating that KRT76 is downregulated prior to tumor development and its potential association with hyperproliferation in the formation of preneoplastic lesions." (PMID 23936238, 2013). "High KRT76 expression is associated with increased tumor susceptibility." (PMID 35836921, 2022). "We therefore suggest that upon loss of Krt76 and the consequent increase in Tregs, there is a failure in anti-tumour immunity that may be caused by an exaggerated suppression of anti-tumour-associated antigen-reactive lymphocytes." (PMID 31225508, 2019). "However, we have shown that in response to 4NQO treatment Krt76−/− mice are more predisposed to developing tumours in those sites where Krt76 is normally expressed, namely the tongue and squamous stomach." (PMID 30143634, 2018). "Loss of Krt76 increases carcinogen-induced tumours in tongue and squamous stomach." (PMID 30143634, 2018). "The major effect of Krt76 deletion on tumour susceptibility may therefore be via enhanced accumulation of Tregs." (PMID 30143634, 2018). "To determine whether the loss of Krt76 directly impacts tumour incidence in the oral cavity, we treated control (wild-type Krt76+/+ and heterozygous Krt76+/−) and Krt76−/− mice with a synthetic carcinogen 4NQO14 that mimics the carcinogenic effects of tobacco and alcohol ingestion." (PMID 30143634, 2018). "On the other hand, the genes TNF and KRT76 were significantly upregulated and overexpressed in the T1 group, which indicates their role as tumor suppressor genes, inhibiting tumor progression and invasion." (PMID 38539520, 2024). "Analysis of the tumour microenvironment within hyperplastic and dysplastic lesions showed increased immune cell infiltrate, higher numbers of infiltrating Tregs and decreased ratios of Teff, suggesting a higher inhibition of Teff in the Krt76−/− tumours." (PMID 31225508, 2019). "Quantitation of 4NQO-induced carcinogenesis revealed that DT treatment accelerated tumour formation in both control and Krt76−/− mice." (PMID 30143634, 2018). "We conclude that Krt76 ablation accelerates 4NQO-induced tumour progression in the tissues where Krt76 is expressed, namely the oral cavity and squamous stomach." (PMID 30143634, 2018). "We provide evidence for a previously unidentified role of Krt76 in regulating immunity in mice and demonstrate its importance in tumour progression." (PMID 30143634, 2018). "The number of Tregs increased in hyperplasias and dysplasias of Krt76−/− tongue compared to controls and there was a marked accumulation of Tregs in tumour stroma (arrowheads, h)." (PMID 30143634, 2018). "Nevertheless, even when tumours developed within the same mouse, some lesions had lost Krt76 expression whereas others retained it." (PMID 30143634, 2018). "In support of a positive role for Treg in 4NQO carcinogenesis, we found that partial depletion of donor Tregs in chimeric mice led to an increase in total Tregs and a corresponding acceleration of tumour formation, both in Krt76−/− and control mice." (PMID 30143634, 2018). "Anti-tumour function of dendritic cells is suppressed through IL-1044 and we found IL-10 to be upregulated in Krt76−/− mice, particularly after 4NQO treatment." (PMID 30143634, 2018). "qRT-PCR analysis revealed significant downregulation of KRT76 RNA in tumor samples compared to normal samples." (PMID 23936238, 2013). "Therefore, genetic ablation of Krt76 protein increases tumour incidence in tongue and squamous stomach." (PMID 31225508, 2019).
tumor (continued). "Krt76−/− mice exhibit a marked inflammatory phenotype with systemic components and are more prone to tumourigenesis, suggesting a previously unidentified role for Krt76 in regulating immunity and emphasising its importance in tumour progression." (PMID 31225508, 2019). "We conclude that loss of Krt76 did not compromise the integrity and barrier properties of tongue and stomach epithelia and that the increased tumour incidence in Krt76−/− mice is not linked to defective epithelial barrier formation." (PMID 30143634, 2018). "Immunofluorescence labelling for Foxp3 revealed an increase of Tregs in both tongue and squamous stomach of Krt76−/− mice compared to control mice, whether normal or tumour-bearing tissue." (PMID 30143634, 2018). "We evaluated KRT76 expression by qRT-PCR in normal and tumor tissues of the oral cavity." (PMID 23936238, 2013). "Thus, future studies to investigate the contributing role of KRT76 in light of other tumor driving events are warranted." (PMID 23936238, 2013). "In Krt76−/− stomach, the number of local CD45+ cells increased in the stroma adjacent to 4NQO-induced tumours." (PMID 30143634, 2018). "IHC analysis also demonstrates a heterogeneous loss of epithelial markers, including epithelial cell adhesion molecule (EpCAM) or Keratin 76 (Krt76), in clinical specimens of HNSCC or oral SCCs, respectively, leading to more aggressive tumor progression and altered immune landscape." (PMID 31024913, 2019). "None of the Krt76+/+ or Krt76+/− control mice developed tumours in the stomach by 28 weeks from the start of 4NQO treatment." (PMID 30143634, 2018). "However, when all the mice in each cohort had developed tumours and were subjected to end-point analysis, the total number of Tregs was significantly increased in DT-treated compared to PBS-treated DEREG/Krt76−/− mice." (PMID 30143634, 2018). "In contrast to the Krt76−/− model, in which increased tumor incidence was not due to epithelial barrier malfunction but to an accumulation of Tregs in the oral epithelium, the Casp8−/− mouse model showed defective epithelial barrier formation and an immune infiltrate enriched in neutrophils." (PMID 39625985, 2024).
infection (1 paper, 2014). The state of being infected such as from the introduction of a foreign agent such as serum, vaccine, antigenic substance or organism. "Loss of KRT76 leads to the acquisition and infection of skin wounds which fail to properly resolve over time." (PMID 25340345, 2014). "Loss of Krt76 results in the rapid appearance of extensive non-healing wounds (especially at sites of active grooming), and the subsequent infection of these lesions contributes significantly to morbidity and mortality in the mice." (PMID 25340345, 2014).
KRT76 also shares sentences with these, for which no sentence is quoted: cardiac arrest (2 papers); epidermolytic hyperkeratosis (2); amyotrophic lateral sclerosis (1); autoimmune disease (1); bacterial infection (1); chronic kidney disease (1); chronic periodontitis (1); delirium (1); depression (1); diabetes mellitus (1); dysplasia (1); epidermolytic ichthyosis (1); epilepsy (1); Hypercalcemia (1); Infertility (1); intracerebral haemorrhage (1); leukoplakia (1); migraine (1); neurodevelopmental disorder (1); nonepidermolytic palmoplantar keratoderma (1); osteoporosis (1); plantar wart (1); respiratory failure (1); Sepsis (1); skin disorder (1); Splenomegaly (1); White sponge nevus (1).